RCN3 (reticulocalbin 3)
Description:
Probable molecular chaperone assisting protein biosynthesis and transport in the endoplasmic reticulum. Required for the proper biosynthesis and transport of pulmonary surfactant-associated protein A/SP-A, pulmonary surfactant-associated protein D/SP-D and the lipid transporter ABCA3 (By similarity). By regulating both the proper expression and the degradation through the endoplasmic reticulum-associated protein degradation pathway of these proteins plays a crucial role in pulmonary surfactant homeostasis (By similarity). Has an anti-fibrotic activity by negatively regulating the secretion of type I and type III collagens. This calcium-binding protein also transiently associates with immature PCSK6 and regulates its secretion.
Synonyms: RLP49
Tractability: Antibody: UniProt predicts a signal peptide or a membrane-spanning region. PROTAC: ubiquitination databases record sites on it; its protein half-life has been measured.
Gene: Protein-coding gene on chromosome 19 (49,526,534 to 49,546,962, forward strand). Ensembl gene ENSG00000142552.
Subcellular location: Endoplasmic reticulum lumen
Subcellular location (Human Protein Atlas): Endoplasmic reticulum; Vesicles
Gene Ontology:
Molecular function: calcium ion binding; protein binding
Biological process: collagen biosynthetic process; positive regulation of peptidase activity; protein secretion; regulation of phosphatidylinositol 3-kinase/protein kinase B signal transduction; ERAD pathway; lung epithelium development; phospholipid homeostasis; protein transport; surfactant homeostasis
Cellular component: endoplasmic reticulum; endoplasmic reticulum lumen
Genetic constraint (gnomAD): Loss-of-function variants: 41 observed, 30.24 expected, observed/expected ratio (o/e) 1.36, 90% interval 1.05 to 1.75. The upper end of that interval is the gene's LOEUF score, 1.75, which puts it in group 6 of 6, group 1 being the genes least tolerant of losing a copy. Missense variants: 451 observed, 412.73 expected, observed/expected ratio (o/e) 1.09, 90% interval 1.01 to 1.18. Synonymous variants: 187 observed, 170.82 expected, observed/expected ratio (o/e) 1.09, 90% interval 0.97 to 1.24.
Homologues: Orthologues: macaque RCN3 (98% identical), dog RCN3 (96% identical), pig RCN3 (95% identical), guinea pig RCN3 (94% identical), rat Rcn3 (93% identical), mouse Rcn3 (93% identical), chimpanzee RCN3 (77% identical), zebrafish rcn3 (57% identical), tropical clawed frog rcn3 (56% identical), Drosophila melanogaster scf (44% identical), Caenorhabditis elegans calu-1 (40% identical). Paralogues in human: RCN1 (55% identical), CALU (50% identical), RCN2 (34% identical), SDF4 (26% identical).
Diseases named in the same sentence as RCN3 in open-access papers:
RCN3 is named in the same sentence as 60 diseases in open-access papers, as found by Europe PMC text mining. Sharing a sentence is not in itself a finding about the gene and the disease. The quoted sentences say what the papers report.
colorectal cancer (9 papers, 2021 to 2025). A primary or metastatic malignant neoplasm that affects the colon or rectum. "Single-cell multi-omics sequencing studies identified RCN3 as a biomarker for the poorer prognosis of colorectal cancer." (PMID 37046668, 2023). "In colorectal cancer, analysis on the impact of RCN3 on patients’ prognosis showed that the expression level of RCN3 is an independent risk factor for a poor prognosis and response to chemotherapy." (PMID 38025763, 2023). "Further studies revealed that RCN3 is a poorer prognostic biomarker for colorectal cancer, overexpressed in melanoma, whereas it is downregulated in NSCLC and osteosarcoma." (PMID 37046668, 2023). "The authors highlighted that the overexpressed BGN, RCN3, TAGLN, MYL9 and TPM2 in cancer-associated fibroblast as potential prognostic biomarkers for patients with colorectal cancers." (PMID 36172359, 2022). "We have limits in our experiments still and the mechanism that can help us better understand the effects of RCN3 both in pan-cancer and colorectal cancer, in which we are interested, remains to be explored." (PMID 35651805, 2022). "It has been reported that RCN3 is a biomarker of poorer prognosis of colorectal cancer." (PMID 35651805, 2022). "A previous article reported that fibroblasts with somatic copy number alterations in the TME play synergetic roles in tumor development through complex interactions with cancer cells, and RCN3 is identified as a fibroblast-specific biomarker of poorer prognosis of colorectal cancer (CRC)." (PMID 35651805, 2022). "BGN, RCN3, TAGLN, MYL9, and TPM2 were identified as fibroblast-specific biomarkers with a poor prognosis in colorectal cancer." (PMID 35785171, 2022). "In addition, limited studies reported that RCN3 also plays a role in non-small cell lung cancer (NSCLC), melanoma, osteosarcomas, gliomas, and colorectal cancer." (PMID 35651805, 2022).
pulmonary fibrosis (3 papers, 2023). Chronic progressive interstitial lung disorder characterized by the replacement of the lung tissue by connective tissue, leading to progressive dyspnea, respiratory failure, or right heart failure. "This study aimed to evaluate Rcn3 as a potential marker in differential diagnosis of idiopathic pulmonary fibrosis (IPF) and connective tissue disease-associated interstitial lung disease (CTD-ILD) and in reflecting the severity of disease." (PMID 36800954, 2023). "RCN3 upregulation may cause resistance to IPF treatment and targeting RCN3 could be a novel approach to ameliorate pulmonary fibrosis." (PMID 37710230, 2023). "RCN3 is an ER lumen protein and its deficiency has been reported to exacerbate pulmonary fibrosis." (PMID 36639674, 2023). "Our previous study using Rcn3 AECII-selective deletion mice indicates that Rcn3 in AECII is antifibrotic against bleomycin-induced pulmonary fibrosis via alleviating ER stress-induced AEC apoptosis." (PMID 37710230, 2023). "Although reticulocalbin 3 (Rcn3) has a critical role in alveolar epithelial function as well as in pathogenesis of pulmonary fibrosis, no study has yet examined its diagnostic and prognostic values for interstitial lung disease (ILD)." (PMID 36800954, 2023). "Interestingly, we found a manifest upregulation of Rcn3 in the fibrotic area of the lung from the bleomycin-induced fibrosis mouse model, suggesting a potential role of Rcn3 in fibroblast during pulmonary fibrosis." (PMID 37710230, 2023). "Elevated RCN3 level may contribute to resistance to IPF treatment, so targeting Rcn3 could be a novel therapeutic approach for pulmonary fibrosis." (PMID 37710230, 2023). "Moreover, repressing Rcn3 expression in mouse fibroblasts ameliorates bleomycin-induced lung fibrosis and pulmonary dysfunction in vivo." (PMID 37710230, 2023). "Furthermore, fibroblast-selective Rcn3 in vivo knockdown ameliorated bleomycin-induced lung fibrosis and pulmonary dysfunction." (PMID 37710230, 2023). "The Rcn3 expression in alveolar epithelium is markedly enhanced in bleomycin-induced pulmonary fibrosis, while selective deletion of Rcn3 in type II alveolar epithelial cells (AECIIs) exacerbated bleomycin-induced lung fibrosis, suggesting a protective role of Rcn3 in lung fibrosis." (PMID 36800954, 2023). "In addition, our recent studies indicated the critical roles of Rcn3 in regulating AEC apoptosis and inflammatory response, involving in lung fibrosis and acute lung injury (ALI)." (PMID 37710230, 2023).
esophageal cancer (2 papers, 2022 to 2023). A primary or metastatic malignant neoplasm involving the esophagus. "RCN3 is significantly overexpressed in multiple tumors, such as glioblastoma, gastric cancer, sarcoma, and esophageal cancer." (PMID 37046668, 2023).
glioblastoma (2 papers, 2022 to 2023). The most malignant astrocytic tumor (WHO grade IV). "In this study, we provided evidence that high RCN3 expression is a risk factor for poor prognosis of glioblastoma patients and plays an important role in GSCs proliferation and self-renewal." (PMID 37046668, 2023). "Using public datasets, we identified that RCN3 is upregulated in glioblastoma and associated with poor overall survival." (PMID 37046668, 2023). "Further prognosis correlation analysis using the TIMER2.0 database demonstrated that the RCN3 gene is associated with the prognosis of multiple tumors, including glioblastoma." (PMID 37046668, 2023). "This was consistent with ROC (receiver operating characteristic) curve analysis showing that RCN3 expression is strongly linked with a high diagnostic value for glioblastoma with an AUC (area under curve) of 0.901." (PMID 37046668, 2023). "This study provides evidence that RCN3 is upregulated in glioblastoma and associated with poor overall survival." (PMID 37046668, 2023). "In our study, we observed that expression of RCN3 increased in glioblastoma tissues and was associated with a worse prognosis." (PMID 37046668, 2023). "Importantly, the Kaplan–Meier survival analysis showed that higher RCN3 expression in glioblastoma patients was associated with poorer overall survival." (PMID 37046668, 2023). "Thereafter, we integrated the clinicopathological variables and RCN3 expression level to construct a nomogram to predict the 1-, 3-, and 5-year survival probabilities of glioblastoma patients." (PMID 37046668, 2023). "In summary, we showed that RCN3 is upregulated in glioblastoma, and high RCN3 expression was correlated with clinical progression and worse prognosis." (PMID 37046668, 2023). "Further, in silico analysis of glioblastoma patient datasets showed RCN3 expression correlated with the ribosome, ECM, and immune response pathway genes." (PMID 37046668, 2023). "Since RCN3 is highly expressed in glioblastoma and correlates with worse prognosis, we sought to determine if its expression is elevated in patient-derived GSC models versus human neural stem cells (hNSCs)." (PMID 37046668, 2023). "Next, we compared its expression levels between normal and glioblastoma tissues and found that RCN3 gene and protein levels are significantly higher in glioblastoma compared to normal brain tissues." (PMID 37046668, 2023). "Our study showed that reticulocalbin 3 (RCN3), an ER lumen residing Ca2+ binding protein, is overexpressed in glioblastoma and associated with poor survival rates." (PMID 37046668, 2023). "Further glioblastoma molecular subgroup expression analysis showed that RCN3 is highly expressed in the mesenchymal subtype in TCGA and CGGA data sets." (PMID 37046668, 2023). "Publicly available datasets suggest RCN3 is overexpressed in glioblastoma and portends poor survival rates." (PMID 37046668, 2023). "In silico analysis of glioblastoma patient datasets demonstrated a positive correlation of RCN3 with ribosomal pathway genes." (PMID 37046668, 2023). "Further in silico analysis of TIMER2 glioblastoma patient data sets also suggested that RCN3 showed a positive correlation with stemness marker CD44 and a negative correlation with differentiation markers such as ID4, MAP2, and NTRK5." (PMID 37046668, 2023). "Using mouse orthotopic glioblastoma models, we showed that the knockdown of RCN3 resulted in enhanced survival of tumor-bearing mice." (PMID 37046668, 2023). "Importantly, the knockdown of RCN3 using shRNA significantly enhanced the survival of tumor-bearing mice in orthotopic glioblastoma models." (PMID 37046668, 2023). "Collectively, these results suggest that RCN3 is a novel mediator of glioblastoma progression." (PMID 37046668, 2023). "Our study suggests that RCN3 could be a potential target for the development of a therapeutic intervention in glioblastoma." (PMID 37046668, 2023).
glioblastoma (continued). "Collectively, these results suggest that RCN3 plays a crucial role in glioblastoma progression." (PMID 37046668, 2023). "Altogether, these results suggest that RCN3 is overexpressed in glioblastoma and might play an essential role in glioblastoma pathobiology." (PMID 37046668, 2023). "In this study, we investigated the role of RCN3 in glioblastoma pathogenesis." (PMID 37046668, 2023). "Importantly, RCN3 knockdown significantly increased the survival of mice in the orthotopic glioblastoma model." (PMID 37046668, 2023). "Our study suggests that RCN3 could be a potential therapeutic target in glioblastoma." (PMID 37046668, 2023). "RCN3 expression may be an important diagnostic and prognostic factor, and glioblastoma patients with high RCN3 expression may exhibit poor survival rates compared to low RCN3 expression group; thus, RCN3 will serve as a valuable therapeutic target for patients with glioblastoma." (PMID 37046668, 2023). "However, little is known about the role of RCN3 in glioblastoma." (PMID 37046668, 2023). "However, it is currently unknown whether RCN3 plays a role in glioblastoma progression." (PMID 37046668, 2023). "However, a knowledge gap exists about whether RCN3 plays a role in glioblastoma." (PMID 37046668, 2023).
keloid (2 papers, 2022 to 2023). An irregularly shaped, elevated mark on the skin caused by deposits of excessive amounts of collagen during wound healing. "Of these, CALU and RCN3 showed abnormally high expression levels with lower p values in keloids; while RCN1 was uniquely present in keloids." (PMID 35435317, 2022). "We identified 206 proteins that showed significant differences in expression between keloid scars and normal skin tissues, including RCN3, RCN1, CALU, and PDGFRL which may play an import role in keloid formation." (PMID 35435317, 2022). "The overexpression of RCN3 in keloids was also highlighted in a study of familial keloid." (PMID 35435317, 2022). "In our study, we found CALU, RCN3, and RCN1, the members of CREC protein family which carries out a number of functional activities, including calcium homeostasis and secretory cargo sorting, were significantly upregulated in keloids." (PMID 35435317, 2022).
melanoma (2 papers, 2016 to 2023). A malignant, usually aggressive tumor composed of atypical, neoplastic melanocytes. "Further, RCN3 is overexpressed in melanoma and esophageal squamous cell carcinoma, whereas it is downregulated in NSCLC and osteosarcoma." (PMID 37046668, 2023). "Whereas the role of TNC (tenascin C) and FN1 (fibronectin 1) in melanoma development is well documented, implication of MARCKS, RCN3, BAMBI, PEA3/ETV4 and the FK506 family members FKBP7, FKBP10 and FKBP11 in melanoma progression is unclear." (PMID 27689402, 2016). "Nothing is known about reticulocalbin (RCN3), the protein with highest melanoma expression in the Protein Atlas, but recently, RCN1, a paralog of RCN3, has been found to be a promising tumor marker for renal cell carcinoma." (PMID 27689402, 2016).
non-small cell lung carcinoma (2 papers, 2020 to 2023). A group of at least three distinct histological types of lung cancer, including non-small cell squamous cell carcinoma, adenocarcinoma, and large cell carcinoma. "Hou and coworkers suggested that there is a potential association between the depletion of Rcn3 protein and development of non-small cell lung cancer." (PMID 33051402, 2020). "SHROOM3 and SERPINF1 play a role in kidney transplantation and chronic kidney disease, while RCN3 and NTM are potential prognostic molecules for non‐small cell lung cancer and ovarian cancer, but they have not been explored in kidney tumors." (PMID 37676078, 2023).
sarcoma (2 papers, 2022 to 2023). A usually aggressive malignant neoplasm of the soft tissue or bone. "A significant positive correlation was found between RCN3 expression and CNA in READ, SARC (sarcoma), UCEC (uterine corpus endometrial carcinoma), UCS (uterine carcinosarcoma), UVM (uveal melanoma), GBM, LGG (brain lower grade glioma), MESO (mesothelioma), and OV (ovarian serous cystadenocarcinoma)." (PMID 35651805, 2022).
adrenocortical carcinoma (1 paper, 2022). "RCN3 expression varied significantly in different pathological stages of cancers, including ACC (adrenocortical carcinoma), BLCA (bladder urothelial carcinoma), BRCA, COAD, ESCA, HNSC, READ (rectum adenocarcinoma), SKCM (skin cutaneous melanoma), and THCA (thyroid carcinoma)." (PMID 35651805, 2022).
bacterial Sepsis (1 paper, 2025). "Reticulocalbin 3 (Rcn3) regulates the NF-κB/NLRP3/inflammasome axis, thereby protecting AECs and alleviating bacterial Sepsis-Associated ALI." (PMID 40842982, 2025).
breast carcinoma (1 paper, 2022). "The results showed higher expression of RCN3 total protein in tumor samples of colon cancer, breast cancer, and clear cell RCC than in normal samples but the opposite result was obtained in UCEC." (PMID 35651805, 2022).
cervical squamous cell carcinoma (1 paper, 2022). A squamous cell carcinoma arising from the cervical epithelium. "In contrast, the expression of RCN3 was below that in normal control tissues in KICH (kidney chromophobe) and CESC (cervical squamous cell carcinoma and endocervical adenocarcinoma)." (PMID 35651805, 2022).
diabetes (1 paper, 2025). "Variations in RCN3 were shown to be associated with the blood level of fructosamine—an important biomarker for diabetes." (PMID 41465472, 2025).
infarction (1 paper, 2026). A localised pathological necrosis of tissue resulting from obstruction of the blood supply usually by a thrombus, an embolus, or vascular torsion. "Although the functional interaction between Rcn3 and PCSK6 remains to be fully elucidated, these observations raise the possibility that post-infarction proteolytic processing of Rcn3 may influence its anti-fibrotic activity, warranting further investigation." (PMID 41597278, 2026).
lymphoma (1 paper, 2025). A malignant (clonal) proliferation of B- lymphocytes or T- lymphocytes which involves the lymph nodes, bone marrow and/or extranodal sites. "Conversely, HLA-ABC–positive lymphomas consisted of a larger proportion of the CD4+ T cell–rich RCN3 and PD-1+ cell–rich RCN4 (adj." (PMID 40772779, 2025).
myocardial infarction (1 paper, 2026). Gross necrosis of the myocardium, as a result of interruption of the blood supply to the area, as in coronary thrombosis. "Using unbiased transcriptomic profiling of cardiac T cell subsets after myocardial infarction, we identified reticulocalbin 3 (Rcn3) as one of the most selectively and robustly upregulated genes in neonatal CD4+Foxp3+ T (T-reg) cells." (PMID 41597278, 2026). "Given the pronounced spatial heterogeneity after myocardial infarction, particularly in neonatal hearts, this approach does not allow precise attribution of Rcn3-dependent effects to the infarct core, border zone, or remote myocardium." (PMID 41597278, 2026).
pancreas tumor (1 paper, 2022). "It is worth nothing that all ACC, breast invasive cases, and pancreas tumor cases with gene alteration (>2%, >1%, >1% frequency, respectively) had copy number amplification of RCN3." (PMID 35651805, 2022).
uterine cancer (1 paper, 2022). Primary or metastatic malignant neoplasm involving the uterine corpus and/or the cervix. "The highest alteration frequency of RCN3 (>4%) appears for patients with uterine cancers, in which “mutation” is the primary genetic alteration type." (PMID 35651805, 2022).